KLKB1 (kallikrein B1)
Description:
Participates in the surface-dependent activation of blood coagulation. Activates, in a reciprocal reaction, coagulation factor XII/F12 after binding to negatively charged surfaces. Releases bradykinin from HMW kininogen and may also play a role in the renin-angiotensin system by converting prorenin into renin.
Synonyms: PKK; KLK3; PKKD; PPK
Tractability: Small molecule: an approved drug acts on it; a structure with a bound ligand is known; a high-quality ligand is known; it belongs to a druggable protein family. Antibody: an approved drug acts on it; its Gene Ontology location is reachable by antibodies, with high confidence; UniProt places it where antibodies can reach, with medium confidence; UniProt predicts a signal peptide or a membrane-spanning region. PROTAC: its protein half-life has been measured; a small molecule that binds it is known. Other modalities: an approved drug acts on it.
Target class: Serine protease; Enzyme; Serine protease PA clan; Serine protease S1A subfamily; Protease
Gene: Protein-coding gene on chromosome 4 (186,225,424 to 186,258,476, forward strand). Ensembl gene ENSG00000164344.
Subcellular location: Secreted
Pathways (Reactome):
Disease: Defective SERPING1 causes hereditary angioedema; Defective factor XII causes hereditary angioedema
Immune System: FXIIa activates plasma kallikrein-kinin system; Regulation of FXIIa and plasma kallikrein activity
Extracellular matrix organization: Activation of Matrix Metalloproteinases
Hemostasis: FXIIa, PKa-dependent activation of coagulation pathway
Gene Ontology:
Molecular function: protein binding; serine-type endopeptidase activity; serine-type peptidase activity
Biological process: plasminogen activation; positive regulation of fibrinolysis; Factor XII activation; proteolysis; zymogen activation
Cellular component: extracellular exosome; extracellular region; plasma membrane
Genetic constraint (gnomAD): Loss-of-function variants: 41 observed, 54.64 expected, observed/expected ratio (o/e) 0.75, 90% interval 0.58 to 0.97. The upper end of that interval is the gene's LOEUF score, 0.97, which puts it in group 4 of 6, group 1 being the genes least tolerant of losing a copy. Missense variants: 606 observed, 651.99 expected, observed/expected ratio (o/e) 0.93, 90% interval 0.87 to 0.99. Synonymous variants: 236 observed, 224.92 expected, observed/expected ratio (o/e) 1.05, 90% interval 0.94 to 1.17.
Gene-disease validity (ClinGen):
ClinGen rates the evidence that KLKB1 causes each of these diseases.
inherited prekallikrein deficiency (autosomal recessive): Definitive. An instance of prekallikrein deficiency that is caused by an inherited modification of the individual's genome.
Homologues: Orthologues: chimpanzee KLKB1 (99% identical), macaque KLKB1 (95% identical), dog KLKB1 (80% identical), rabbit KLKB1 (80% identical), pig KLKB1 (80% identical), mouse Klkb1 (76% identical), rat Klkb1 (75% identical), guinea pig KLKB1 (62% identical), zebrafish f9a (18% identical), tropical clawed frog cfi (18% identical), zebrafish habp2 (18% identical), Drosophila melanogaster CG31266 (12% identical), and 1 more. Paralogues in human: F11 (57% identical), HGFAC (22% identical), F12 (22% identical), C1R (20% identical), C1S (19% identical), F7 (19% identical), CFI (19% identical), F9 (18% identical), F10 (18% identical), PRSS55 (17% identical), C1RL (13% identical), PRSS51 (13% identical), and 4 more.
Diseases named in the same sentence as KLKB1 in open-access papers:
KLKB1 is named in the same sentence as 60 diseases in open-access papers, as found by Europe PMC text mining. Sharing a sentence is not in itself a finding about the gene and the disease. The quoted sentences say what the papers report.
hereditary angioedema (8 papers, 2022 to 2026). Hereditary angioedema (HAE) is a genetic disease characterized by the occurrence of transitory and recurrent subcutaneous and/or submucosal edemas resulting in swelling and/or abdominal pain. "Hereditary angioedema (HAE) is a genetic disorder caused by an autosomal dominant mutation in KLKB1, encoding for prekallikrein, which is produced in the liver and circulates in the blood, where it is converted to kallikrein by the protease Factor XII." (PMID 37190012, 2023). "CRISPR/Cas and base editing machinery can already be delivered via lipid nanoparticles to hepatocytes to delete specific genes (e.g., KLKB1 for hereditary angioedema and PCSK9 for familial hypercholesterolaemia), with promising results in clinical trials." (PMID 41562671, 2025). "Recent clinical trials have demonstrated excellent safety profiles using in vivo CRISPR/Cas9 editing of the KLKB1 gene to treat patients with hereditary angioedema and editing the HSV-1 gene to treat patients with herpetic stromal keratitis." (PMID 39200190, 2024). "Intellia Therapeutics developed NTLA-2002, an in vivo therapy for hereditary angioedema, which is delivered intravenously and comprises LNPs containing Cas9 mRNA and sgRNA specific to KLKB1." (PMID 37190012, 2023). "For example, KLKB1 protein is the target for ecallantide, which is used to treat hereditary angioedema." (PMID 36388766, 2022). "Promising current clinical trials for direct in vivo Cas9 gene editing strategies are based on lipid nanoparticle (LNP)-mediated Cas9 delivery for the treatment of hereditary angioedema and for transthyretin amyloidosis, by disrupting liver expression of KLKB1 or TTR, respectively." (PMID 41271724, 2025). "In 2021, Intellia Therapeutics dosed NTLA‐2002 to patients in a phase I/II clinical trial for hereditary angioedema (HAE), where NTLA‐2002 acts as a gene therapy that inactivates kallikrein B1 (KLKB1) and prevents HAE attacks." (PMID 37166046, 2023).
angioedema (7 papers, 2020 to 2025). Swelling involving the deep dermis, subcutaneous, or submucosal tissues, representing localized edema. "PKa deficiency due to KLKB1 mutations leads to vascular bleeding and has been implicated in hereditary angioedema and hemorrhagic stroke." (PMID 38731959, 2024). "Its mechanism involves targeted disruption of the KLKB1 gene in hepatocytes, leading to decreased production of plasma kallikrein and bradykinin and thereby reducing angioedema attacks." (PMID 41377389, 2025). "However, KLKB1 may increase the risk of cerebral hemorrhagic transformation and angioedema." (PMID 36959823, 2023). "We also found several proteins (e.g., KLKB1, F12) that were negatively correlated with angioedema." (PMID 35746486, 2022). "Moreover, first studies have shown that variants in bradykinin-related genes (e.g., KLKB1) influence some of the phenotypic variations observed in HAE, and it cannot be excluded that such variants may also play a role in the occurrence of ACEi/ARB-induced angioedema." (PMID 35923707, 2022). "The pathologic attractor corresponding to the hereditary form of the disease called angioedema is the fixed point PF10, at which there is the absence of the gene SERPING1 and the presence of the genes KLKB1 coding for kallikrein B1 and KNG coding for kininogen." (PMID 33286034, 2020).
COVID-19 (6 papers, 2020 to 2022). A disease caused by infection with severe acute respiratory syndrome coronavirus 2. "Conversely, components of the coagulation cascade (SERPINA5, SERPIND1, PROC, CPB2, F13B, and KLKB1) and proteins involved in cholesterol metabolism were downregulated with the severity of COVID-19 but increased over time." (PMID 35958562, 2022). "Moreover, C1INH that is involved in KLKB1 regulation also presented similar levels in patients with COVID-19 and HC." (PMID 35812405, 2022). "According to these criteria, we found four procoagulants (ADAMTS13, F11, HGFAC, KLKB1) and two anticoagulants (C1QTNF1, SERPINA5), whose expression may predispose males and older individuals to COVID-19-related coagulopathy and severe COVID-19 disease." (PMID 32751741, 2020). "A number of proteins identified as outcome predictors have also been shown to be differentially expressed in sepsis, including SAA1, CRP, SERPINA1, KLKB1, and A2M, indicating a general inflammatory signature rather than specific markers of COVID-19." (PMID 36812516, 2022). "Similarly, two key proteins of the coagulation system, thrombin (F2) and plasma kallikrein (KLKB1), known to be decreased in severe COVID-19, further decreased over time in non-survivors, while increasing in survivors." (PMID 36812516, 2022).
Hypertension (5 papers, 2016 to 2017). The presence of chronic increased pressure in the systemic arterial system. "In sum, we postulate that the G allele of a KLKB1 SNP, rs3733402, is associated with reduced hypertension and coronary artery disease." (PMID 27200353, 2016). "Two another upregulated DEGs (Klkb1 and Vwf) in the complement and coagulation cascades are known as associated with both hypertension and kidney diseases." (PMID 26821914, 2016). "Plasma prekallikrein (Klkb1 gene) was considered as a risk marker for hypertension and nephropathy in type 1 diabetes." (PMID 26821914, 2016). "When the best-fit model based on the Akaike information criterion controlled for age, weight, gender, hypertension, and history of angina, the G allele of KLKB1 rs3733402 that is associated with less plasma kallikrein activity correlated with reduced history of CVD." (PMID 27200353, 2016). "Model selection for the best fit for the association between SNP rs7104980 (PRCP gene) and SNP rs3733402 (KLKB1 gene) with hypertension and a history of diabetes, cigarette use, or angina." (PMID 27200353, 2016). "Expression of either REN or KLKB1 was regulated in cell line and rodent models of hypertension in response to oxidative stress, interleukin or arterial blood pressure changes." (PMID 26969407, 2016).
atherosclerosis (4 papers, 2021 to 2024). A disease characterized by the build-up of fatty material and calcium deposition in the arterial wall resulting in partial or complete occlusion of the arterial lumen. "KLKB1, serine protease inhibitors, among others, are associated with atherosclerosis and the coagulation cascade." (PMID 39802657, 2024). "Point variants of KLKB1 have been shown to associate with amyloid beta levels and thus atherosclerosis." (PMID 33512769, 2021). "Interestingly, ablation of Klkb1 dampened the progression of atherosclerosis in mice on an Apoe-deficient background." (PMID 38792081, 2024). "Furthermore, the KLKB1/CYP4V2 locus has been associated with atherosclerosis, and the KLKB1 and F12 genes are both involved in several proteolytic reaction cascades in the cardiovascular system." (PMID 33961016, 2021).
deep venous thrombosis (4 papers, 2013 to 2022). "KLKB1 rs3087505 is associated with venous thrombosis and this SNP is in linkage disequilibrium (LD) with two F11 SNPs (rs2036914, rs3756008) also associated with thromboembolism." (PMID 27200353, 2016). "We then performed additional colocalization analyses based on the obtained conditional association statistics, and identified a positive colocalization between the OPN association signal at rs4253311 at the KLKB1 locus and rs1593 for deep venous thrombosis (DVT; H4: p12 = 0.96)." (PMID 35385482, 2022). "Among others, downstream analyses revealed colocalization of the OPN association signal at SPP1 with expression in pancreas tissue, and at KLKB1 with various plasma proteins in trans, and with phenotypes (bone disorder, deep venous thrombosis) in human tissue." (PMID 35385482, 2022). "Single nucleotide polymorphisms (SNPs) in a 4q35.2 locus that harbors the coagulation factor XI (F11), prekallikrein (KLKB1), and a cytochrome P450 family member (CYP4V2) genes are associated with deep venous thrombosis (DVT)." (PMID 24066149, 2013). "Rs3733402 is not in LD with two F11 SNPs associated with venous thrombosis even though KLKB1 SNP rs3087505 from the 3′prime UT region is." (PMID 27200353, 2016).
Stroke (4 papers, 2017 to 2022). Sudden impairment of blood flow to a part of the brain due to occlusion or rupture of an artery to the brain. "In another study, low levels of SERPINA1, PLG, KLKB1, ITIH4, and APOL1 in serum of patients with lacunar stroke were associated with poor prognosis and increased risk of recurrent stroke or myocardial infarction and cognitive decline." (PMID 31242583, 2019). "Eight protein-disease pairs were ranked as the most valuable findings after the filtering, which include IL-7R and TNFSF12 level on asthma; ACE level on COPD; AIF1 level on HF; SERPINF1 level on stroke; and SERPINE2, F11, KLKB1, and ABO level on VTE." (PMID 36388766, 2022). "Using public drug databases, we curated drugs targeting those proteins in a direction compatible with a beneficial therapeutic effect against stroke based on MR estimates and identified such drugs for VCAM1, F11, KLKB1, GP1BA, LAMC2 (inhibitors) and PROC (activators)." (PMID 36180795, 2022).
prekallikrein deficiency (3 papers, 2015 to 2024). A condition characterized by the congenital or acquired deficiency of prekallikrein. "Certain mutations in KLKB1, mutated in one of five CT-pNENs, cause prekallikrein deficiency, and KLKB1 was mutually exclusive with ATRX, DAXX, and MEN1 of pancreatic neuroendocrine tumors (PanNets)." (PMID 37771441, 2023).
Alzheimer disease (2 papers, 2017 to 2024). A progressive, neurodegenerative disease characterized by loss of function and death of nerve cells in several areas of the brain leading to loss of cognitive function such as memory and language. "Protein measurements for cognition in Alzheimer's disease provide the clue for the significant relation of KLKB1 with the caudate nucleus (FDG CN)." (PMID 38468964, 2024). "We discovered age-dependent genetic effects, established associations between vascular-related genes (KLKB1, F12, PLIN2) and midlife plasma aβ levels, and identified a plausible Alzheimer’s Disease candidate gene (ITPRIP) influencing cell death." (PMID 28704393, 2017).
asthma (2 papers, 2014 to 2022). "Presence of the major (T) allele was associated with increased KLKB1 activity in the control (P<0.01), asthma (P<0.01), and COPD populations (P<0.001)." (PMID 24249636, 2014). "Using a validated activity assay, the KLKB1 rs4253238 genotype was associated with KLKB1 activity using a fluorescent substrate in 10 randomly chosen homozygote subjects (TT vs. CC) from each of the control, asthma, and COPD populations." (PMID 24249636, 2014). "We next determined the biological activity of KLKB1 on primary HBECs, which are key effector cells for remodeling in asthma and COPD." (PMID 24249636, 2014). "Two of the pairs, SERPINF1 on asthma and KLKB1 on VTE, were not reported in any of the pQTL studies and are not under clinical investigation yet, which we have therefore suggested are completely novel protein-disease pairs identified in this study." (PMID 36388766, 2022). "Although the relationship between KLKB1 and uPAR levels was not unique to diseased populations, we identified overall reduced KLKB1 activity in the asthma and COPD populations, which may at least in part contribute to the elevated scuPAR levels detected in these disease populations." (PMID 24249636, 2014).
coagulopathy (2 papers, 2016 to 2020). "In the coagulation system, it has been reported that even the homozygous deficiency of the KLKB1 loci results in no discernible coagulopathy." (PMID 26969407, 2016).
deep vein thrombosis (2 papers, 2013 to 2021). "In the present study, we searched for evidence for the existence of common regulatory elements within a locus that has been linked to deep vein thrombosis and harbors F11, KLKB1 and CYP4V2 i.e. the 4q35.2 locus." (PMID 24066149, 2013).
ischemic stroke (2 papers, 2019 to 2025). A stroke disorder caused by obstruction of blood flow to the brain, due to thrombotic (local blood clot formation) or embolic (due to a blood clot or other material traveling from another site) event. "Second, there was stronger pairwise colocalization evidence with ischemic stroke for F11 (posterior probability, 0.99) compared with KLKB1 (posterior probability, 0.80)." (PMID 40188416, 2025). "Similarly, KLKB1, which was reduced in the cardioembolic vs. large-vessel stroke and in the CBS-deficient patients, was found to be reduced in Han Chinese ischemic stroke patients." (PMID 31242583, 2019).
melanoma (2 papers, 2022 to 2023). A malignant, usually aggressive tumor composed of atypical, neoplastic melanocytes. "KLKB1 may influence prognosis of melanoma patients by regulating malignant cells." (PMID 36059641, 2022).
adenocarcinoma of the prostate (1 paper, 2025). "In contrast, we observed minimal differences in the levels of prostate and prostate cancer-associated proteins, including KLKB1, KLK2, KLK3, ACP3, and SLC45A3, which are markers of conventional adenocarcinoma of the prostate." (PMID 39910169, 2025).
age-related macular degeneration (1 paper, 2016). Age-related loss of vision in the central portion of the retina (macula), secondary to retinal degeneration. "The 8 known pQTLs along with the kallikrein pQTL are associated with a variety of phenotypes, including age-related macular degeneration (C3b), activated partial thromboplastin times (F12), serum metabolites (KLKB1), binding of LBP to lipopolysaccharide (LBP), and plasma plasminogen levels (LP(a))." (PMID 27329291, 2016).
Allergy (1 paper, 2016). An allergy is an immune response or reaction to substances that are usually not harmful. "Genetic variation at the KLKB1 locus (encoding for plasma pre-kallikrein or Fletcher factor; EC 3.4.21.34) was previously most widely investigated for its roles in coagulation and allergy." (PMID 26969407, 2016).
Arthritis (1 paper, 2016). Inflammation of a joint. "Further, plasma kallikrein (antibodies to the beta subunit (KLKB1) were identified) is part of a cascade that results in the activation of bradykinins, which are considered to be potent inflammatory mediators with relevance in arthritis." (PMID 27729089, 2016).
atrial fibrillation (1 paper, 2023). A disorder characterized by an electrocardiographic finding of a supraventricular arrhythmia characterized by the replacement of consistent P waves by rapid oscillations or fibrillatory waves that vary in size, shape and timing and are accompanied by an irregular ventricular response. "A decrease in KLKB1 increases the risk of atrial fibrillation." (PMID 36959823, 2023).
colitis (1 paper, 2018). Inflammation of the colon. "To determine the role of pKal in DSS-induced colitis, we generated a mouse strain with a disrupted Klkb1 gene, which encodes pKal (Klkb1−/− mice)." (PMID 29467753, 2018). "Kng1−/− mice, B1RB2R−/− mice, or Klkb1−/− mice had significant protection against TNBS-induced colitis, as evidenced by the amelioration of body weight loss, colon length shortening, and histological changes." (PMID 29467753, 2018). "After treatment with DSS, Klkb1−/− mice showed a significant decrease in body weight loss and DAI, and exhibited significant attenuation in colon shortening and destructive colitis compared to Klkb1+/+ mice." (PMID 29467753, 2018). "To understand the protective phenotypes observed in Kng1−/−, Klkb1−/−, and B1RB2R−/− mice in DSS-induced colitis, we measured bradykinin levels in the plasma which was prepared using EDTA as an anticoagulant." (PMID 29467753, 2018).